GGCT (gamma-glutamylcyclotransferase)
Diseases named in the same sentence as GGCT in open-access papers (continued):
Sharing a sentence is not in itself a finding about the gene and the disease.
cancer (continued). "GGCT has attracted the attention of cancer research due to its involvement in the malignant phenotype." (PMID 30011933, 2018). "Here, we show that depletion of GGCT induces cellular senescence in different cancer cells, inhibits cell growth, and promotes cell death." (PMID 27658708, 2016). "Chromosome 7 open reading frame 24 (C7orf24) was originally identified as a highly expressed protein in various types of cancer, and later shown to be a γ-glutamylcyclotransferase (GGCT)." (PMID 27658708, 2016). "Our results shed new light on the mechanisms underlying the anticancer effects of GGCT-targeting and highlight the potential of GGCT blockade as a therapeutic strategy to induce cellular senescence in cancer cells." (PMID 27658708, 2016). "A growing body of evidence indicates that GGCT is a promising candidate as a therapeutic target and biomarker in cancer." (PMID 27658708, 2016). "Although some discrepant findings were observed, a high-level expression of GGCT protein was observed in a wide range of cancers." (PMID 26339607, 2015). "Although the upregulation of GGCT in cancer cells has been reported, the role of GGCT in cancer cells is still unclear." (PMID 26339607, 2015). "In several previous studies GGCT, a critical component of the GSH pathway, has been implicated as a cancer marker with a potential role in cell proliferation." (PMID 25818003, 2015). "A number of relationships between cancer and GGCT have been reported by some researchers and the role of this molecule in cancer has attracted attention." (PMID 26339607, 2015). "Inhibition of GGCT expression suppresses the proliferation of cancer cells, and mild adverse events are expected from a recent study." (PMID 26339607, 2015). "This could implicate a specific function of GGCT mRNA expression in cancer initiation or early-stage cancer progression." (PMID 31400748, 2019). "However, GGCT deficiency is compatible with normal mouse development, suggesting that GGCT can be a cancer-specific therapeutic target." (PMID 31400748, 2019). "We found significant GGCT genetic amplification in human LUAD and other cancers, importantly GGCT, maybe the target gene for chromosome 7p or 7p14.3 amplification in cancer." (PMID 31400748, 2019). "Similarly, other groups have reported that GGCT depletion inhibited the growth of cancer cell lines in vitro including osteosarcoma, lung cancer, glioma, gastric cancer, colorectal cancer, and ovarian cancer cells." (PMID 30011933, 2018). "In addition, they studied the expression of GGCT in other cancers and described high expression of GGCT in 58% of uterine cervical cancers, 38% of lung cancers, and 72% of colon cancers." (PMID 30011933, 2018). "GGCT upregulation in clinical cancer samples has been reported." (PMID 30011933, 2018). "They found that GGCT knockdown significantly induced cellular senescence with SA-β-gal staining, a specific marker for senescent cells, in various cancer cells including MCF7, MDA-MB-231 (breast cancer), PC3, LNCaP (prostate cancer), HeLa (cervical cancer), and A172 (glioblastoma)." (PMID 30011933, 2018). "Following appropriate research, molecular targeting of GGCT through small inhibitors might become a promising clinical treatment used in cancer therapy in the near future." (PMID 30011933, 2018). "We found that GGCT knockdown induces significant cellular senescence in various cancer cells." (PMID 27658708, 2016). "However, GGCT is a very attractive target molecule because its high expression has been observed in a wide range of cancer types." (PMID 26339607, 2015). "Furthermore, inhibition of cell-growth was observed by inhibiting GGCT expression with RNA interference in several types of cancer cell lines possessing high-level expressions of GGCT." (PMID 26339607, 2015). "GGCT (C7orf24) was also reported as an upregulated protein in various cancers." (PMID 26339607, 2015).
cancer (continued). "However, it is still unknown if GGCT expression up-regulation is simply a by-product of cancer formation or if GGCT up-regulation is required for cancer evolution." (PMID 31400748, 2019). "Pro-GA, as a cell membrane permeable GGCT inhibitor, might become a promising novel therapeutic agent against various cancers expressing high levels of GGCT such as breast, ovarian, cervical, lung, urinary bladder, colon cancers, osteosarcoma, esophageal squamous cell carcinoma, and glioma." (PMID 30011933, 2018). "Indeed, depletion of GGCT inhibits the aggressive phenotype of various cancers." (PMID 30011933, 2018). "In addition to its enzymatic role, GGCT may be a multifunctional molecule that is involved in the growth of cancer." (PMID 26339607, 2015). "In summary, our study not only identifies an oncogenic function of GGCT but also identifies a novel regulator of GSH metabolism, with implications for further understanding of oncogenic stress and cancer treatment." (PMID 31400748, 2019). "However, the cellular events associated with GGCT depletion have not been fully characterized to date, and the mechanisms underlying its inhibitory effect on the growth of cancer cells remain unknown." (PMID 27658708, 2016). "Taken together, our results indicate that depletion of GGCT induces CDK inhibitor(s) that mediate cell cycle arrest and subsequent cellular senescence in various cancer cells, leading to the significant suppression of cell growth." (PMID 27658708, 2016). "In this study, GGCT and MRPL9 were shown to be involved in regulating the biological behavior of PTC tumor cells and promoting the further development of cancer, suggesting that GGCT and MRPL9 may serve as potential biomarkers." (PMID 36233293, 2022). "However, it was still not known if GGCT up-regulation is a simple consequence of cancer progression, or GGCT is selected to be up-regulated during cancer initiation and progression, and thus can have cancer-driving ability." (PMID 31400748, 2019). "However, the role that GGCT, as an enzyme in the gamma-glutamyl cycle, has in the activity of cancer cells is still not known." (PMID 26339607, 2015). "However, the consequence of GGCT up-regulation in cancer prognosis is still not well studied." (PMID 31400748, 2019).
tumor (6 papers, 2015 to 2025). "GGCT expression was significantly upregulated in tumor tissues, while AOX1, NT5E, PPP1R12A, and PTGS2 were significantly downregulated compared to normal tissues in the TCGA cohort." (PMID 34484299, 2021). "Gamma-glutamylcyclotransferase is expressed higher than normal in many tumor tissues." (PMID 36626444, 2022). "They produced tumor-bearing mice by subcutaneous implantation of EBC-1, a lung squamous cell carcinoma cell line, and then administered anti-GGCT siRNA to the tumor using a needle-free jet injection and obtained significant tumor regression." (PMID 26339607, 2015). "Finally, IHC analysis confirmed that ThyC patients’ tumor tissues had an overall higher level of GGCT expression compared to that in the non-cancerous control tissues." (PMID 37707688, 2023).
infection (1 paper, 2016). The state of being infected such as from the introduction of a foreign agent such as serum, vaccine, antigenic substance or organism. "In addition, infection of lenti-shGGCT resulted in a remarkable increase of MGC80-3 cell number in the sub-G1 phase suggesting that GGCT depletion might induce cell apoptosis." (PMID 27905872, 2016).
GGCT also shares sentences with these, for which no sentence is quoted: osteosarcoma (3 papers); colon cancer (2); thyroid cancer (2); Alzheimer disease (1); anemia (1); cervical cancer (1); cleft lip (1); glioblastoma (1); glioma (1); Hypertension (1); lip (1); lymph node metastasis (1); Obesity (1); oral cancer (1); osteoporosis (1); ovarian carcinoma (1); polycystic ovary syndrome (1); premature ovarian failure (1); serous ovarian cancer (1); Splenomegaly (1); thrombophilia (1); thyroid tumor (1); tobacco use disorder (1); type 2 diabetes (1); Type I diabetes (1).